PTH (parathyroid hormone)
Diseases named in the same sentence as PTH in open-access papers (continued):
Sharing a sentence is not in itself a finding about the gene and the disease.
hypoparathyroidism (continued). "Taken as a group, at the time of DFO test, there was little evidence that these patients had hypoparathyroidism; mean (SEM) serum PTH was 48.5 (6.8) pM whilst mean (SEM) Hb concentration was maintained at 9.8 (0.3) g/dl." (PMID 21992770, 2011). "We have seen significant improvements in permanent hypoparathyroidism throughout this project, which was not an anticipated outcome based on preoperative SSKI or perioperative calcium carbonate administration or calcium and PTH monitoring." (PMID 35720874, 2022). "However, serum ferritin level in patients with hypoparathyroidism did not correlate with the levels of serum FGF23, calcium, phosphorous, PTH, 25(OH) D, 1,25(OH)2D3, and FEPh (P > 0.05)." (PMID 33198660, 2020). "Hence, the present study on hypoparathyroid patients and normal population provides an opportunity to observe whether the phosphaturic effect of FGF-23 is independent of PTH or not." (PMID 32398014, 2020).
diabetes (313 papers, 2006 to 2026). "Previous studies have explored the association between PTH and diabetes, but the findings have been inconsistent." (PMID 39791168, 2025). "Factors independently associated with increased risk include diabetes mellitus, obesity, elevated calcium–phosphorus product, high PTH levels, vitamin D supplementation, cinacalcet therapy, and warfarin use." (PMID 41472909, 2025). "This bone characteristic is influenced by various factors, including deficient PTH signaling, exposure to aluminum, protein-bound uremic toxins (PBUTs), and diabetes mellitus." (PMID 40669844, 2025). "In our study, we examined the impact of the pandemic on blood values related to dyslipidemia, diabetes, and parathyroid hormone levels as a marker for calcium deficiency." (PMID 40768087, 2025). "Numerous factors contributing to PTH hyporesponsiveness, which also induces low bone turnover, include deficient PTH, uremic toxins like indoxyl sulfate, malnutrition, inflammation, and diabetes." (PMID 40669844, 2025). "Patients diagnosed with diabetes mellitus are prone to major depression, and the disease is associated with elevated PTH and linked to bone disease." (PMID 38681457, 2024). "Patients with higher intact PTH levels tended to be younger; were less likely to have diabetes as the cause of kidney failure; and had longer dialysis duration, higher BMI, higher creatinine, lower calcium, and higher phosphorus levels." (PMID 39430172, 2024). "The presence of several modifiable factors, such as diabetes mellitus, inadequate nutrition, low hemoglobin, and parathyroid hormone, are associated with decreased response to hepatitis B vaccine in CKD." (PMID 38675820, 2024). "Age was negatively associated with serum albumin, calcium, phosphate, PTH, and creatinine and positively associated with diabetes, CVD, and dyslipidemia." (PMID 38820324, 2024). "SGLT2 inhibitors are also thought to promote renal phosphate reabsorption, increase fibroblast growth factor 23 and PTH, and act by decreasing active vitamin D, causing calciuria; however, the effects of diabetes medications on bone health need further study." (PMID 37047250, 2023). "Our data further show that diabetes duration and modifiable risk factors of bone health, specifically 25(OH)D, PTH, and BMI, are associated with HR-pQCT parameters." (PMID 36936151, 2023). "Logistic regression analysis showed that age, diabetes mellitus, coronary artery calcification, lower serum magnesium, lower serum calcium, and lower parathyroid hormone levels were associated with valve calcification." (PMID 38093238, 2023). "Our study was strengthened by the following two factors.: First, we performed propensity matching to balance many of the important risk factors for death, namely age, diabetes, dialysis vintage, and sex, between the low PTH and SHPT groups." (PMID 35634511, 2022). "In subgroup analysis, U-shaped association between PTH level and all-cause mortality was found in both diabetes mellitus (DM) group and non-Diabetes Mellitus (NDM) group." (PMID 35380083, 2022). "Higher BPV positively associated with diabetes status and serum PTH levels and negatively associated with the adequacy of dialysis (Kt/V) and SGA scores." (PMID 36415108, 2022). "First, our findings showed that ESRD patients with the LGALS3 rs4644 CC and rs4652 AA genotypes and also the CAA haplotype had a higher risk for lower hemoglobin and lower PTH level, and occurrence of diabetes mellitus and arterial hypertension." (PMID 35807161, 2022). "We concluded that the effect of PTH on the mortality rate of hemodialysis patients is much weaker than that of other strong, traditionally-recognized risk factors, such as age, diabetes history, and dry weight." (PMID 35634511, 2022). "In summary, LGALS3 rs4644 CC and rs4652 AA genotypes were significantly associated with a higher risk for lower hemoglobin, higher level of parathyroid hormone, and also occurrence of diabetes mellitus and arterial hypertension." (PMID 35807161, 2022).
diabetes (continued). "As for PTH, previous study suggested that serum PTH levels were associated with cardiovascular mortality in patients with diabetes." (PMID 34602077, 2021). "Data on joint associations between vitamin D and PTH with diabetes and related risk factors are limited." (PMID 34531372, 2021). "PD patients with low serum PTH levels were significantly older, with a higher proportion of diabetes mellitus as the primary cause of ESRD." (PMID 33514340, 2021). "In conclusion, our study reported that a lower serum level of OC and a lower serum level of PTH were independently associated with a higher prevalence of diabetes and a lower prevalence of cholesterol abnormalities in Chinese postmenopausal women." (PMID 33833796, 2021). "A recent observational cohort study showed a significant association between PTH levels and cardiovascular mortality in patients with diabetes, which was true after adjustment for classical CAD risk factors." (PMID 34602077, 2021). "The strongest strength of our study is the finding of combined low OC and low PTH associating with higher risks of diabetes and cholesterol abnormalities than low OC or low PTH alone." (PMID 33833796, 2021). "Low 25(OH)D and high PTH were jointly associated with increased risk of diabetes among white women only." (PMID 34531372, 2021). "In a univariate Cox proportional hazards model the following parameters were associated with an increased risk for peritonitis: higher age (> 65 years), diabetes mellitus, low serum PTH levels." (PMID 33514340, 2021). "Second, we only investigated explore the association of serum 25OHD, Ca and PTH levels with the risk of CAD in patients with diabetes from a genetic point of view." (PMID 34602077, 2021). "In the logistic regression model, both OC and PTH were negatively associated with the prevalence of diabetes (odds ratio [OR], 95% confidence interval [95% CI]: 0.967, 0.948–0.986 for OC and 0.986, 0.978–0.994 for PTH)." (PMID 33833796, 2021). "High blood glucose concentration associated with diabetes suppressed OC secretion directly by suppressing osteoblast or indirectly by suppressing PTH secretion." (PMID 33833796, 2021). "Logistic regression analysis reported that either increasing OC (OR = 0.967, 95% CI = 0.948–0.986) or increasing PTH (OR = 0.986, 95% CI = 0.978–0.994) was independently associated with decreasing prevalence of diabetes." (PMID 33833796, 2021). "A logistic regression model was used to investigate the association of OC, PTH, or 25(OH)D with the prevalence of diabetes and dyslipidemia." (PMID 33833796, 2021). "We subsequently performed a MR study to explore the association of serum 25OHD, Ca and PTH levels with the risk of CAD in patients with diabetes." (PMID 34602077, 2021). "This study aimed to further evaluate the joint associations of 25-hydroxyvitamin D [25(OH)D] and parathyroid hormone (PTH) with risks of diabetes and related cardiometabolic comorbidities among white and black women." (PMID 34531372, 2021). "Canaglifozin and dapaglifozin, SGLT2 inhibitors for the treatment of diabetes, have been reported to increase PTH levels in association with increased serum phosphate and FGF23." (PMID 32751307, 2020). "BMI ≥ 25 kg/m2 at transplantation was associated with PTH > 300 pg/mL at transplantation (p = 0.0002) and with pre-transplant diabetes (p < 0.0001)." (PMID 30794689, 2019). "RLS in ESRD patients has been variably reported to be associated with female gender, duration of dialysis, diabetes mellitus, iron deficiency anemia, parathyroid hormone, increased body mass index (BMI), and increased homocysteine." (PMID 30925907, 2019). "The association of low 25(OH)D with high risk of diabetes also persisted after stratification for PTH level, regular strenuous exercise, and metabolic syndrome." (PMID 29672520, 2018). "The main risk factors for ABD are age, uremia, excessive PTH suppression from vitamin D analogues, calcium overload, PD, and diabetes mellitus." (PMID 28152049, 2017).
diabetes (continued). "Moderate and high PA levels were associated with lower prevalence of hypertension and diabetes mellitus, and lower concentrations of serum ferritin, parathyroid hormone, and alkaline phosphatase." (PMID 28327105, 2017). "The variables that were associated with an increased risk of phosphate of >1.78 mmol/L were sex, diabetes mellitus, binder dose taken, percent phosphate absorption, and PTH." (PMID 28218647, 2017). "PTH excess is strongly associated with prevalent and incident cardiovascular risk factors such as hypertension, diabetes, and cardiovascular diseases." (PMID 26377856, 2016). "Parathyroid hormone (PTH) has also been implicated in several chronic complications of diabetes including retinopathy and nephropathy, as well as in renal disease in non-diabetics." (PMID 26074879, 2015). "Our analyses revealed, on the other hand, that levels of PTH in women with diabetes were positively related with all-cause mortality independently of vitamin D, PWV and carotid IMT." (PMID 26078787, 2015). "It is also associated with age, the presence of diabetes mellitus and hypertension, serum phosphorus and PTH levels in this patient population." (PMID 26459001, 2015). "In women with diabetes, on the other hand, levels of PTH were positively related to all-cause mortality when performing the corresponding analyses, while vitamin D levels were without such statistical significance." (PMID 26078787, 2015). "To further determine the associations among age, diabetes, and PTH levels, we divided the study population into five age groups (<50; 50–59; 60–69; 70–79; ≥80)." (PMID 23865464, 2013). "Diabetes and age were independently associated with serum PTH levels (interaction: diabetes × age groups, p=0.138)." (PMID 23865464, 2013). "The objective of this study was to quantify the associations between 25(OH)D and parathormone (PTH) plasma levels and obesity, the presence of MetS, diabetes or atherogenic dyslipidemia (AD) in a large sample of individuals with different degrees of adiposity." (PMID 23228198, 2012). "In this multicentre observational retrospective study in southern China, which included 446 CKD5 patients, we found that levels of intact PTH may be associated with mineral metabolism, diabetes, and anemia." (PMID 39791168, 2025). "Notably, diabetes and elevated PTH levels are particularly significant risk factors for CAC progression." (PMID 40314886, 2025). "Our study has also shown an association between low PTH and mortality in patients with diabetes." (PMID 36719878, 2023). "Furthermore, as we have shown in our study, PTH is associated with other CVRFs such as hypertension, dyslipidemia, diabetes, and smoking." (PMID 37959184, 2023). "By multivariate logistic regression analysis, we found that LGALS3 rs4644 CC and rs4652 AA genotypes were significantly associated with a higher risk for lower hemoglobin, higher level of parathyroid hormone, and also occurrence of diabetes mellitus and arterial hypertension." (PMID 35807161, 2022). "As some variables are known to be associated with PhA, such as age, sex, diabetes, glomerular filtration rate, BMI, hemoglobin, physical activity, calcium x phosphorus, PTH, and ultrasensitive CRP a hierarchical multiple logistic regression was performed to predict positive CAC score." (PMID 35990362, 2022). "Moreover, BPV was positively associated with diabetes status and blood PTH levels and negatively associated with the adequacy of dialysis (Kt/V) and SGA scores in the volume overload group." (PMID 36415108, 2022). "Additionally, age, diabetes, coronary heart disease, calcium × phosphate product, and intact parathyroid hormone levels were independently associated with AVC and MVC." (PMID 35042976, 2022).
diabetes (continued). "Weighted Cox proportional hazards analyses and weighted logistic regression models were used to examine the joint associations of 25(OH)D and PTH with incident diabetes and prevalence of other diabetes-related cardiometabolic comorbidities (including CKD, hypertension, or obesity)." (PMID 34531372, 2021). "However, few studies have specifically examined the joint associations of circulating 25(OH)D and PTH levels with diabetes or related comorbid cardiometabolic conditions in a multiethnic cohort." (PMID 34531372, 2021). "Previous reports found that diabetes impaired the PTH secretion, which might be caused by high glucose concentrations or AGEs." (PMID 33833796, 2021). "We conducted the subgroup analysis stratified by low eGFR, CKD, gender, age, BMI, hypertension, and diabetes to further explore the association of DII with the PTH level and HP in different population settings by stratified weighted multivariate regression analysis and tested the interactions." (PMID 34249998, 2021). "Indirect causes of developing diabetes mellitus may be increased inflammation as well as enhanced calcemic hormones like PTH especially in obese and vitamin D-deficient subjects." (PMID 34950730, 2021). "Among Chinese postmenopausal women, a lower serum level of OC was associated with a higher prevalence of diabetes and lower serum cholesterol levels, and a low PTH concentration could magnify these associations." (PMID 33833796, 2021). "Furthermore, in the absence of large-scale, long-term RCT data, our findings provide strong evidence against a causal role for low serum 25OHD levels, elevated serum Ca and PTH levels in CAD susceptibility in patients with diabetes." (PMID 34602077, 2021). "Intermittent PTH administration diminishes alveolar bone loss and sclerostin expression in osteocytes, but increases osteoid formation and mineralization, suggesting that intermittent PTH administration attenuates diabetes-aggravated alveolar bone loss by the induction of bone formation." (PMID 29544500, 2018). "When entering major risk factors in Cox regression analyses, vitamin D levels were negatively related to all-cause mortality in men with diabetes, independently of baseline age, PTH, HbA1c, waist circumference, mean 24 h systolic ambulatory blood pressure and apoB levels." (PMID 26078787, 2015). "Elderly patients, those with longer dialysis durations, dialysis shift, and those with high levels of parathyroid hormone (PTH) or diabetes mellitus are at higher risk of insomnia; however, the dialysis type and biochemical parameters are not important determinants of insomnia." (PMID 20546577, 2010). "Their calcium, phosphorus and PTH levels may vary significantly according to the progression of kidney failure, to dialysis and to other associated conditions such as diabetes, the diet and others." (PMID 18852973, 2008). "Notably, PTH itself has been reported to be associated with incident diabetes, although the mechanism remains unclear." (PMID 41050279, 2025). "In addition, some studies reported that PTH levels were associated with diabetes." (PMID 39791168, 2025). "In joint modeling analysis, time-varying PTH, age ≥65 years, and diabetes mellitus (DM) were significantly associated with an increased risk of IHD, whereas ARB and statin use were associated with a reduced risk." (PMID 40429305, 2025). "A decreased amount of serum 25(OH)D, calcitriol [1,25(OH)2D], and raised parathyroid hormone (PTH) can increase intracellular calcium in adipocytes, which can stimulate lipogenesis, predisposing the individual to further weight gain and thus increasing the risk of diabetes." (PMID 38887504, 2024). "One proposed pathogenic mechanism is that an increase in PTH levels is accompanied by an increase in intracellular calcium, thereby reducing insulin-stimulated tissue glucose uptake, leading to insulin resistance, followed by glucose intolerance and, ultimately, diabetes." (PMID 37959184, 2023).